SNX30 (sorting nexin family member 30)
Description:
Involved in the regulation of endocytosis and in several stages of intracellular trafficking. Together with SNX4, involved in autophagosome assembly.
Synonyms: ATG24A
Tractability: Antibody: UniProt places it where antibodies can reach, with medium confidence. PROTAC: ubiquitination databases record sites on it; its protein half-life has been measured.
Gene: Protein-coding gene on chromosome 9 (112,750,760 to 112,881,671, forward strand). Ensembl gene ENSG00000148158.
Subcellular location: Early endosome membrane
Subcellular location (Human Protein Atlas): Cytosol; Nucleoli; Nucleoplasm
Gene Ontology:
Molecular function: protein binding; phosphatidylinositol binding
Biological process: positive regulation of autophagosome assembly; protein transport; endocytic recycling; mitophagy; piecemeal microautophagy of the nucleus; reticulophagy
Cellular component: early endosome; early endosome membrane; phagophore assembly site; cytoplasm; cytoplasmic vesicle
Genetic constraint (gnomAD): Loss-of-function variants: 19 observed, 39.84 expected, observed/expected ratio (o/e) 0.48, 90% interval 0.33 to 0.7. The upper end of that interval is the gene's LOEUF score, 0.7, which puts it in group 2 of 6, group 1 being the genes least tolerant of losing a copy. Missense variants: 502 observed, 503.71 expected, observed/expected ratio (o/e) 1, 90% interval 0.93 to 1.07. Synonymous variants: 176 observed, 187.9 expected, observed/expected ratio (o/e) 0.94, 90% interval 0.83 to 1.06.
Homologues: Orthologues: chimpanzee SNX30 (100% identical), macaque SNX30 (99% identical), pig SNX30 (97% identical), dog SNX30 (97% identical), mouse Snx30 (95% identical), rat Snx30 (93% identical), guinea pig SNX30 (91% identical), rabbit SNX30 (88% identical), tropical clawed frog snx30 (81% identical), zebrafish snx30 (76% identical). Paralogues in human: SNX7 (44% identical), SNX18 (23% identical), SNX33 (21% identical), SNX9 (21% identical), SNX2 (21% identical), SNX1 (20% identical), SNX4 (20% identical), SNX5 (16% identical), SNX32 (15% identical), SNX6 (15% identical), SNX8 (15% identical), SNX11 (11% identical), and 3 more.
Diseases named in the same sentence as SNX30 in open-access papers:
SNX30 is named in the same sentence as 6 diseases in open-access papers, as found by Europe PMC text mining. Sharing a sentence is not in itself a finding about the gene and the disease. The quoted sentences say what the papers report.
epilepsy (1 paper, 2025). A brain disorder characterized by episodes of abnormally increased neuronal discharge resulting in transient episodes of sensory or motor neurological dysfunction, or psychic dysfunction. "In contrast, some genes (RPL4, MTPAP, and SNX30) that are downregulated in the PZ also showed downregulation in epilepsy samples in the TLE versus healthy scRNA dataset." (PMID 39541170, 2025).
glomerulosclerosis (1 paper, 2022). A hardening of the kidney glomerulus caused by scarring of the blood vessels. "In the transcriptomics analyses, as expected, all 13 significant correlations with the level of fibrosis were observed for tubular gene expression, and the two observed correlations for glomerulosclerosis were for glomerular expression of SNX30 and COLEC11." (PMID 35763030, 2022). "On the contrary, in our transcriptomics data higher tubular SNX30 was correlated with higher eGFR (p=5.8×10−14) and lower level of fibrosis (p<2.0×10−16); glomerular expression was correlated with less glomerulosclerosis (p=8.0×10−5)." (PMID 35763030, 2022).
osteosarcoma (1 paper, 2015). A usually aggressive malignant bone-forming mesenchymal neoplasm, predominantly affecting adolescents and young adults. "Downregulation of miR-143 promotes osteosarcoma cell invasion through MMP-13 upregulation, and silencing of miR-133a reduces the malignancy of CD133high osteosarcoma-initiating cell population through restoring the expression of multiple target genes (SGMS2, UBA2, SNX30, and ANXA2)." (PMID 25912304, 2015).
SNX30 also shares sentences with these, for which no sentence is quoted: cancer (1 paper); fibrosis (1); lung adenocarcinoma (1).